PCSK9 (proprotein convertase subtilisin/kexin type 9)
Diseases named in the same sentence as PCSK9 in open-access papers (continued):
Sharing a sentence is not in itself a finding about the gene and the disease.
Hypercholesterolemia (continued). "Indeed, despite aggressive treatment of hypercholesterolaemia using statins and proprotein convertase subtilisin-kexin type 9 (PCSK9) inhibitors, over one third of patients still have hs-CRP levels > 3 mg/L which is associated with an increased risk of future major adverse cardiac events (MACE)." (PMID 34862118, 2021). "Considering that the blood cholesterol levels were much lower than those in high-cholesterol diet-fed apoE-deficient mice and wild-type mice carrying gain-of-function mutations of PCSK9, hypercholesterolemia is not likely to contribute to the augmented AAA development in O-HFD." (PMID 34571873, 2021). "Thus, although PCSK9 inhibitors have been mainly developed for the treatment of hypercholesterolemia, early studies have shown that PCSK9 inhibitors could reduce steatosis biomarkers in some patients with both familiar hypercholesterolemia and NAFLD." (PMID 35052726, 2021). "Therefore, inhibition of PCSK9 plays an important role in hypercholesterolemia treatment." (PMID 34359627, 2021). "Nevertheless, it must be considered that the improvement of the arterial stiffness could be simply related to LDL-C levels, as recently demonstrated in patients with familial hypercholesterolemia treated with high-intensity statins in combination with PCSK9 inhibitors or ezetimibe." (PMID 33923431, 2021). "Familial hypercholesterolemia (FH) occurs due to an altered pathway of receptor-mediated LDL uptake due to mutations of the LDL receptor, the ApoB protein, the low-density lipoprotein receptor adapter protein 1 (LDLRAP1), or the proprotein convertase subtilisin/kexin type 9 (PCSK9) gene." (PMID 34832111, 2021). "However, clinical trials with proprotein convertase subtilisin/kexin type 9 inhibitors in patients with atherosclerotic vascular disease have shown that hypercholesterolemia in humans should be defined in terms of plasma cholesterol levels that are much lower than previously accepted." (PMID 31484164, 2019). "This post-hoc analysis examined whether age modified the efficacy and safety of alirocumab, a PCSK9 inhibitor, in patients with heterozygous familial hypercholesterolemia (HeFH), using pooled data from four 78-week placebo-controlled phase 3 trials (ODYSSEY FH I, FH II, LONG TERM, and HIGH FH)." (PMID 30734207, 2019). "PCSK9 is an individual from the mammalian serineproprotein convertase family that commonly capacities in theproteolytic handling and development of secretory proteins.PCSK9 was the principal relative to be embroiled in anoverwhelmingly acquired type of hypercholesterolemia." (PMID 30108423, 2018). "This implies that PCSK9 genome editing technique might be a novel strategy that may be used to permanently alter the human genome for the prevention of coronary heart disease in patients with hypercholesterolemia." (PMID 30761308, 2018). "Hence, PCSK9 has been considered as a new target for hypercholesterolemia treatment." (PMID 29230236, 2017).
Hypercholesterolemia (continued). "However, there is still a need to evaluate whether PCSK9 inhibition yields benefits on cardiovascular endpoints, for patients with primary hypercholesterolemia." (PMID 27095708, 2016). "Thus, PCSK9 inhibition is an attractive target for treating hypercholesterolemia." (PMID 27115873, 2016). "Finally, while PCSK9 mutations are well known in causing hypercholesterolemia, recent research shows that absence of PCSK9 can provide a protective benefit against melanoma due to lower circulating LDLc." (PMID 24669769, 2014). "Familial hypercholesterolemia (FH; OMIM#143890) is an autosomal-dominant disease caused by a deficiency in low-density lipoprotein (LDL) receptor (ADH1) activity or in LDL-related genes (ApoB and PCSK9), which leads to obviously elevated LDL cholesterol (LDL-C) and triglyceride concentrations." (PMID 25424010, 2014). "These molecular disturbances are characteristic of diet-induced hypercholesterolemia and steatosis: HFD has been reported to elevate PCSK9 expression, contributing to reduced hepatic LDL uptake and hyperlipidemia." (PMID 41596930, 2026). "PCSK9 inhibition has emerged as an effective strategy for lowering LDL cholesterol, particularly in patients with familial hypercholesterolemia or those intolerant to statins." (PMID 41596290, 2026). "Especially, Merck’s enlicitide decanoate (formerly MK-0616) is poised to be the first oral PCSK9 inhibitor for lowering LDL-C, targeting patients with hypercholesterolemia." (PMID 41596290, 2026). "At present, data on serum levels of PCSK9 in IBD are inconsistent and analyses of well-described, large cohorts that can correct for confounding factors such as hypercholesterolemia and severe liver disease are needed." (PMID 40265438, 2025). "PCSK9 is the best-established target, with monoclonal antibodies and siRNA-based agents used to lower LDL cholesterol in hypercholesterolemia." (PMID 41446579, 2025). "CVD prevention strategies include the management of hypercholesterolemia, predominantly through low-density lipoprotein cholesterol (LDL-c) lowering medications including statins and proprotein convertase subtilisin/kexin type 9 (PCSK9) inhibitors." (PMID 40052268, 2025). "Proprotein convertase subtilisin/kexin type 9 (PCSK9) is a key modulator of low-density lipoprotein cholesterol (LDL-C) levels and emerged as an attractive therapeutic target for the treatment of hypercholesterolemia and cardiovascular diseases." (PMID 40942107, 2025). "Proprotein convertase subtilisin/kexin type 9 (PCSK9) inhibitors, initially developed for lipid-lowering therapy in patients with hypercholesterolemia, were recently investigated for their potential role in cancer prevention." (PMID 40364115, 2025). "The most frequently edited gene was PCSK9 (32%, 18 studies), a key regulator of LDL cholesterol, reflecting its prominence in hypercholesterolemia models." (PMID 40465697, 2025). "For example, an orally available macrocyclic peptide inhibitor of proprotein convertase subtilisin/kexin type 9 (PCSK9), MK-0616, is about to enter phase III clinical trials for the treatment of hypercholesterolaemia." (PMID 39822773, 2025). "Another therapeutic acting as a Pcsk9 inhibitor, human monoclonal antibody—alirocumab, was approved by the FDA in 2015 for the treatment of heterozygous familial hypercholesterolemia and atherosclerosis." (PMID 40725196, 2025). "PCSK9 inhibitors (PCSK9i) clearly demonstrate LDL-C lowering and is hugely beneficial in patients with familial hypercholesterolemia and for secondary prevention of acute cardiovascular events in high-risk patients with atherosclerotic cardiovascular disease." (PMID 39623109, 2025).
Hypercholesterolemia (continued). "Neutralising PCSK9 with monoclonal antibodies attenuates CCR2-mediated chemotaxis and dampens pro-inflammatory monocyte activation in familial hypercholesterolemia." (PMID 41008547, 2025). "Both alirocumab and evolocumab, whichare PCSK9 inhibitors, have been approved by theFood and Drug Administration (FDA) for treatingpatients with familial hypercholesterolemia, statinintolerance or contraindication, and ASCVD." (PMID 40821628, 2025). "Inclisiran is another first-in-class small interfering RNA (siRNA) against PCSK9 that has been approved by both the US Food and Drug Administration (FDA) and the European Medicines Agency (EMA) for the treatment of hypercholesterolemia." (PMID 39623109, 2025). "Proprotein convertase subtilisin/kexin type 9 (PCSK9), for example, has developed into a novel therapeutic target for hypercholesterolemia and related cardiovascular illnesses, as well as a crucial enzyme in lipid metabolism." (PMID 38540127, 2024). "Therefore, it might be possible to use PNA against PCSK9 in the treatment of hypercholesterolemia." (PMID 38338741, 2024). "We studied PCSK9-GOF pigs, a well-established swine model of hypercholesterolemia, to evaluate target-organ effects of dyslipidemia." (PMID 39094771, 2024). "Based on the proven efficacy and safety profile of existing monoclonal antibodies, we have developed a peptide-based vaccine against PCSK9, VXX-401, as an alternative option to treat hypercholesterolemia and prevent ASCVD." (PMID 38216056, 2024). "One LNP utilizing GalNAc is inclisiran, a PCSK9 siRNA GalNAc-LNP that has demonstrated lasting reductions in LDL cholesterol for up to 6 months and is currently approved for use in patients with hypercholesterolaemia." (PMID 38696700, 2024). "Currently, evolocumab and alirocumab, 2 monoclonal antibodies targeting PCSK9, have received Food and Drug Administration (FDA) approval for treating hypercholesterolemia." (PMID 39324018, 2024). "The first one aims at controlling circulating PCSK9 levels and/or its interaction with liver LDL receptors to reduce blood cholesterol and to prevent the hypercholesterolemia-induced BBB damage and the consequent alterations in the brain lipid contents." (PMID 39769398, 2024). "For individuals with familial hypercholesterolemia (FH) who face elevated ASCVD risks due to high cholesterol levels, anti-PCSK9 monoclonal antibodies have been in use since 2015 in Belgium." (PMID 39770423, 2024). "PCSK9 inhibitors induce a marked reduction in LDL cholesterol levels and subsequent cardiovascular events, especially beneficial for patients with familial hypercholesterolemia or statin intolerance." (PMID 39131016, 2024). "Among them, inclisiran is the first-in-class small interfering RNA (siRNA) against PCSK9 that has been approved by both the US Food and Drug Administration (FDA) and the European Medicines Agency (EMA) for the treatment of hypercholesterolemia." (PMID 37111334, 2023). "We also conducted an additional gene co-localisation analysis, identifying four genes, namely CELSR2, PCSK9, LPA, and APOE, co-localised with hypercholesterolaemia and IHD." (PMID 38144368, 2023).
Hypercholesterolemia (continued). "Overexpression of miR-483 in mice liver increased hepatic LDL receptor levels by targeting PCSK9, leading to decreased plasma total cholesterol and LDL cholesterol levels, suggesting that microRNA-483 ameliorates hypercholesterolemia." (PMID 36980601, 2023). "The siRNA targeting PCSK9 inclisiran has already been approved by both the FDA and EMA, for the treatment of hypercholesterolemia in USA and Europe, respectively." (PMID 35900635, 2022). "At present, revusiran and inclisiran target transthyretin and PCSK9 gene for the treatment of hereditary ATTR amyloidosis and hypercholesterolemia, respectively." (PMID 35200353, 2022). "Currently, PCSK9 monoclonal antibodies include alirocumab and evolocumab, which are approved by the US Food and Drug Administration (FDA) for the treatment of hypercholesterolemia, including primary hypercholesterolemia and familial hypercholesterolemia." (PMID 36230934, 2022). "Almost two decades ago, several studies identified a role for PCSK9 in the regulation of hepatic low-density lipoprotein-receptor (LDL-R) protein levels and a link to hypercholesterolemia." (PMID 35162992, 2022). "Current lipid-lowering agents such as ezetimibe, PCSK9 inhibitors, BDA, and inclisiran are used in treating hypercholesterolemia as monotherapy or combination concerning safety, efficacy, and Cardiovascular benefits." (PMID 36348882, 2022). "Accordingly, PCSK9 inhibitory antibodies and siRNA potently reduce LDL cholesterol to unprecedented low levels and are approved for treatment of hypercholesterolemia." (PMID 36733269, 2022). "The observed degree of base editing at this Pcsk9 splice donor with v4 BE-eVLPs (>60%) is thought to be sufficient for the reduction of serum LDL and treatment of hypercholesterolemia." (PMID 35021064, 2022). "Additional clinical validation of the activity of DLinMC3DMA was observed in a Phase 1 clinical trial of ALN-PCS02, containing an siRNA directed against proprotein convertase subtilisin/kexin type 9 (PCSK9), for the treatment of severe hypercholesterolemia." (PMID 35214130, 2022). "We aimed to evaluate the impact of PCSK9 plasma levels on pulse wave velocity (PWV) and the effect of PCSK9 inhibitors (PCSK9-i) on circulating PCSK9 and PWV in a cohort of heterozygous familial hypercholesterolemia (HeFH) subjects." (PMID 35454151, 2022). "We aimed to evaluate the effects of PCSK9 inhibitors (PCSK9-i) on CD34+CPCs and pulse wave velocity (PWV) in a cohort of heterozygous familial hypercholesterolemia (HeFH) subjects." (PMID 35885020, 2022). "The aim of this observational study was to investigate the effect of PCSK9 inhibitors (PCSK9-i) treatment on HDL-CEC and serum CLC in patients with familial hypercholesterolemia (FH)." (PMID 35928226, 2022).
Hypercholesterolemia (continued). "Inclisiran, a siRNA-based drug to inhibit the expression of PCSK9, has shown efficacy in phase III trials that enrolled over 3000 patients with ASCVD and 482 patients with familial hypercholesterolemia." (PMID 35371605, 2022). "A study observed that patients with hypercholesterolemia showed increased expression of CCR2 on classical monocytes, but treating them with PCSK9 inhibitors significantly lowered the expression of the same receptor." (PMID 34884827, 2021). "Recently, proprotein convertase subtilisin/kexin type 9 (PCSK9) has been regarded as an endogenous inhibitor of LDL-C, and anti-PCSK9 monoclonal antibodies have been used for treating hypercholesterolemia." (PMID 33996937, 2021). "Conversely, positive trends were found among PCSK9 quintiles and total, LDL-, HDL-cholesterol, and triglycerides (among the continuous variables), as well as personal histories of hypercholesterolemia and hypertriglyceridemia (among the categorical variables)." (PMID 34356905, 2021). "Inhibition of PCSK9 in combination with statins and/or ezetimibe provides a highly effective approach for lowering LDL-cholesterol concentrations in patients with hypercholesterolemia." (PMID 33643062, 2021). "Moreover, proprotein convertase subtilisin/kexin type-2 (PCSK9) inhibitors, potent agents against hypercholesterolemia, might enhance the expression of hepatic low-density lipoprotein receptors and accelerate FVIII degradation within the liver, thereby lowering circulating FVIII levels." (PMID 34072487, 2021). "Moreover, it is conceivable that adjustment of dose levels and schedules could further increase editing rates in macaques to those observed in mice, making the PCSK9 base editing approach reported here also suitable for treating patients with familial hypercholesterolemia." (PMID 34012094, 2021). "The basis for this recommendation is the reduced efficacy of PCSK9 inhibition in lowering LDL-cholesterol lowering in these HoFH who were enrolled in the Efficacy and Safety of Evinacumab in Patients With Homozygous Familial Hypercholesterolemia trial." (PMID 33716107, 2021).